HP (haptoglobin)
Diseases named in the same sentence as HP in open-access papers (continued):
Sharing a sentence is not in itself a finding about the gene and the disease.
malaria (continued). "A multivariate negative binomial regression model was used to estimate the impact of haptoglobin genotypes on incidence of uncomplicated malaria in the children’s cohort." (PMID 33243242, 2020). "In particular, haptoglobin has been studied further in the present Nigerian cohort, showing overall depleted levels in severe malaria groups and the data supporting the idea that low haptoglobinaemia is a risk factor in SMA but not CM." (PMID 32336276, 2020). "In 2014, Huang and colleagues conducted a proteomic discovery study in 390 Gambian children and identified a panel of two biomarkers (haptoglobin and lipocalin-2) to discriminate acute respiratory infection from severe malaria with respiratory distress." (PMID 30348160, 2018). "Why is haptoglobin a good biomarker to discriminate malaria from bacterial infection in children with respiratory distress?" (PMID 30348160, 2018). "The combination of haptoglobin and lipocalin-2 discriminated acute respiratory distress from malaria with high sensitivity and specificity (area under the ROC curve of 99% in Gambian children and 82% in Kenyan children)." (PMID 30348160, 2018). "It is intractable to carry-out a large clinical study where HP levels are measured at the initial day of infection, especially in holoendemic high-transmission malaria settings such as ours." (PMID 30510258, 2018). "Differentiating between these two etiological scenarios should provide insights into the role of HP in the establishment of mild or severe malaria syndromes." (PMID 30510258, 2018). "The plasma HP levels at admission in the SMA group are significantly lower when compared to the levels in the other malaria groups SMA < CC (p < 0.0001); SMA < CM (p < 0.001); SMA < UM (p < 0.0001)." (PMID 30510258, 2018). "Our results suggest that Superoxide dismutase, Vitronectin, Titin, Apolipoprotein E, Serum amyloid A, and Haptoglobin are potential predictive markers for malaria severity." (PMID 27090372, 2016). "The anti-inflammatory response during malaria also implies the receptor CD163 which scavenges the complex haemoglobin:haptoglobin, allows heme degradation by HO-1, avoids tissue damage, and facilitates IL-10 secretion." (PMID 26385579, 2015). "Because haptoglobin was undetectable in many children with severe malaria, we analyzed the correlation with ADMA and arginine using Spearman’s method." (PMID 26407009, 2015). "This is likely attributable to malaria-induced generation of plasma haemoglobin and haem that overwhelms both haptoglobin and/or haemopexin pathways, as demonstrated by significantly higher levels of plasma haem prior to the onset of ECM in the KO animals." (PMID 26691827, 2015). "Another potential therapy would involve the use of hemopexin or haptoglobin in adjunctive therapies capable of quenching excessive free heme in malaria patients." (PMID 26555697, 2015). "In malaria-endemic areas, the combination of Lpc-2 with haptoglobin should be prospectively evaluated for use in guiding the clinical management of children with respiratory distress." (PMID 24696240, 2014). "The combination of Lpc-2 and haptoglobin distinguished bacterial versus malaria origin of respiratory distress with high sensitivity and specificity in Gambian children (AUC, 99% [95% confidence interval, 99%–100%]) and Kenyan children (82% [74%–91%])." (PMID 24696240, 2014). "The proportion of children with severe malaria and a high haptoglobin concentration (11 of 41 [27%]) was the major difference observed between the Kenyan and the Gambian study." (PMID 24696240, 2014). "In contrast, the serum concentration of haptoglobin was reduced in malaria-infected individuals, which we verified by western blot assay." (PMID 25372941, 2014). "We observed a bimodal distribution in haptoglobin concentrations (above and below 5 × 106 ng/mL) in children with malaria and respiratory distress and in children with both pneumonia and malaria." (PMID 24696240, 2014).
malaria (continued). "The combination of Lpc-2 and haptoglobin were effective in discriminating between pneumonia and severe malaria with respiratory distress." (PMID 24696240, 2014). "We found that haptoglobin in combination with Lpc-2 was remarkably effective in discriminating between pneumonia and malaria in children with respiratory distress." (PMID 24696240, 2014). "The levels of the hemoglobin and heme scavengers haptoglobin and hemopexin drastically drop in malaria, thalassemia and sickle cell disease which confirm accumulation of free heme in all these conditions albeit their distinct kinetics." (PMID 23029401, 2012). "Haptoglobin and apolipoprotein A-I (Apo A-I) concentrations were directly quantified turbidimetrically in the serum samples of malaria patients (n = 37), healthy subjects (n = 20) and febrile controls (n = 6)." (PMID 22912677, 2012). "Receiver operating characteristic (ROC) curve analysis was carried out to evaluate the individual performance of 3 classifier proteins; apolipoprotein A-I, haptoglobin and retinol-binding protein in malaria prediction." (PMID 22912677, 2012). "Noteworthy was the occurrence of late onset haemolytic anaemia in six patients with severe malaria, characterized by increased reticulocyte counts, unconjugated bilirubin and lactate dehydrogenase and decreased haptoglobin and haemoglobin (Hb) values." (PMID 22462806, 2012). "Individual performance of three classifier proteins; haptoglobin, apolipoprotein A-I and retinol-binding protein in diagnosis of malaria was analyzed using receiver operating characteristic (ROC) curves." (PMID 22912677, 2012). "Contrary to previous reports, the geometric mean concentration of haptoglobin was increased at malaria compared to convalescence (56.13 mg/dl vs 27.50 mg/dl, paired t-test, p<0.0001, n = 231)." (PMID 17426810, 2007). "Generally, results from studies on the relationship between haptoglobin levels and intravascular hemolysis during malaria are inconclusive, and our study confirms that it is difficult to use haptoglobin as a measure of intravascular hemolysis in this endemic area." (PMID 37091678, 2023). "Numerous genotypes of haptoglobin have been reported in malaria endemic populations." (PMID 33243242, 2020). "A systematic liver safety panel, serum LDH, hemolysis panel, hemolysis index, and haptoglobin, along with parasite density and malaria clinical score should comprise VIS safety endpoints, with an appropriate decision tree if clinically relevant effects are detected." (PMID 32314694, 2020). "The evidence that the rs12162087 (g.-1203G > A) genetic variant, with an observed frequency of 0.67 in this predominantly Yoruba Ibadan’s cohort, is associated with plasma HP levels in the malaria-negative CC group is fairly compelling." (PMID 30510258, 2018). "Furthermore, in acquired hypo-haptoglobinemia, induced by malaria or hemolytic disease, HP levels return to normal 2 weeks after the commencement of antimalarial treatment." (PMID 30510258, 2018). "Interestingly, serum abundance of HP was found to be higher in DF patients compared to HC, while its serum level was substantially low in malaria patients." (PMID 28667326, 2017). "Treatments that reduce CFH levels or CFH-mediated oxidative stress, such as haptoglobin or paracetamol respectively, may have potential as an adjunctive therapy to improve kidney function and survival in severe malaria." (PMID 28449641, 2017). "Recent case definition of post-artesunate delayed haemolytic (PADH) syndrome consists of 10 % fall in haemoglobin associated with haptoglobin <0.1 g/L and either an increase in LDH to >390 IL/L or a 10 % rise >7 days after start of treatment with artesunate in naïve patients with severe malaria." (PMID 26502714, 2015). "For instance, haptoglobin is malaria-protective, since it is toxic to P. falciparum-infected RBCs." (PMID 25408684, 2014).
malaria (continued). "ROC analysis revealed that the serum levels of the classifier proteins, particularly Apo A-I and haptoglobin exhibited good correlation with plasmodial infections and could further be investigated as potential surrogate protein markers for malaria." (PMID 22912677, 2012). "Haptoglobin concentrations were analysed at malaria (n = 257, first detection of a confirmed malarial episode, parasite density >500/ul plus temperature >37.5°C) and convalescence (n = 235, 14 days later&no detectable parasites) in individuals with Hp haplotype data available." (PMID 17426810, 2007). "In our study, in cases of confirmed symptomatic malaria (current or record of temperature >37.5°C, and parasite density >500/ul) age was negatively correlated with haptoglobin concentration–perhaps suggesting a decreased acute phase/inflammatory reaction in older children." (PMID 17426810, 2007). "However, during conditions such as sickle cell anemia or malaria, haptoglobin is depleted." (PMID 42133656, 2026). "Whereas HP and HPX exert some level of control over the pathogenic effects of labile heme, other serum heme-binding proteins and/or macromolecules might partake in this defense mechanism that establishes disease tolerance to malaria." (PMID 38307624, 2024). "Furthermore, haptoglobin concentrations have been shown to increase after malaria treatment." (PMID 17426810, 2007). "Neither HP, HPX nor labile heme interfere with parasite burden, suggesting that the HP/HB and HPX/heme scavenging systems contribute to the establishment of disease tolerance to malaria." (PMID 38307624, 2024). "In conclusion, HP and HPX act in an age-dependent manner to prevent the pathogenesis of severe presentation of malaria in mice and presumably in humans." (PMID 38307624, 2024). "This suggests that HP and HPX limit the accumulation of heme–iron in the kidneys of ageing mice, a major driving force in the pathogenesis of malaria AKI." (PMID 38307624, 2024). "This suggests that HP and HPX control systemic iron metabolism during malaria in adult mice." (PMID 38307624, 2024). "The age-dependent protective effect of HP and/or HPX against malaria AKI in mice and the inverse correlation of HPX and heme with renal impairment in P. falciparum malaria are consistent with the age-dependent increase in susceptibility to renal impairment in P. falciparum malaria." (PMID 38307624, 2024). "Here, we tested whether scavenging of extracellular HB and/or labile heme, by haptoglobin (HP) and/or hemopexin (HPX), respectively, counter the pathogenesis of severe presentations of malaria." (PMID 38307624, 2024). "In contrast, severe non-cerebral malaria was associated with lower concentration of circulating HP, but not HPX, compared with uncomplicated malaria." (PMID 38307624, 2024). "Importantly, in the group of symptomatic malaria, aging was significantly related to decreased haptoglobin MDP values only, whereas in the group of asymptomatic malaria, aging specifically reduced the fibrinogen MDP values but not of other markers." (PMID 34727121, 2021). "Overall, the HP levels in the SMA group remain significantly lower at all time points compared to levels in both other malaria groups and the parasite-negative CC group." (PMID 30510258, 2018). "Quite a few differentially abundant proteins such as Haptoglobin (HP), Superoxide dismutase (SOD), Ceruloplasmin (CP), Titin (TTN), Nebulin (NEB), and Vitronectin (VTN) were found to be highly relevant in context of pathophysiology of severe malaria." (PMID 27090372, 2016). "Moreover, the age-dependent renal transcriptional response and protective effect of HP and HPX in Plasmodium-infected mice supports the idea of an age-dependent impairment of tissue damage control mechanisms establishing disease tolerance to malaria." (PMID 38307624, 2024).
malaria (continued). "To determine whether the HP/HB and/or HPX/heme scavenging systems are protective against malaria we combined the analyzes of a pediatric P. falciparum malaria case-control study with experimental models of malaria in mice carrying Hp and/or Hpx genetic deletions." (PMID 38307624, 2024). "This suggests that, in the absence of HP, ⍺1-microglobulin might take a predominant role in scavenging labile heme during malaria." (PMID 38307624, 2024). "To probe the pathologic effect of labile heme in P. falciparum malaria we asked whether targeting extracellular HB and/or labile heme by HP and HPX, respectively, limit the accumulation of labile heme and/or prevent the pathogenesis of severe presentations of malaria." (PMID 38307624, 2024). "Haptoglobin was lower in patients with severe and non-severe knowlesi malaria compared to controls (0.11 g/dL, 0.30 g/dL, and 1.44 g/dL, respectively, p < 0.0001 for both comparisons), and lower in patients with severe compared to non-severe knowlesi malaria (p = 0.004)." (PMID 29872039, 2018). "This was also the case for Hp−/−Hpx−/−Hmox1+/− mice, lacking one Hmox1 allele, suggesting that the extent of renal iron overload imposed by HP and HPX depletion is not sufficient to precipitate the pathogenesis of malaria AKI in adult mice." (PMID 38307624, 2024). "We found that labile heme is an independent risk factor for cerebral and non-cerebral presentations of severe P. falciparum malaria and that HP and HPX act in an age-depended manner to prevent the pathogenesis of non-cerebral severe malaria in mice." (PMID 38307624, 2024). "This suggests that, in contrast to other components of the heme/iron detoxifying pathway, including HO-1, ferritin H chain or ferroportin 1, HP and HPX are not essential to survive malaria in adult mice." (PMID 38307624, 2024). "The concentrations of HP and HPX in serum were indistinguishable in children that developed P. falciparum CM versus those with uncomplicated malaria." (PMID 38307624, 2024). "It is remarkable, however, that negative APPs, as, e.g., haptoglobin, PAI-1, and AP with potentially efficient anti-malaria activity, are decreased during the APR against blood-stage malaria." (PMID 25408684, 2014).
Obesity (36 papers, 2009 to 2025). Accumulation of substantial excess body fat. "For the first time, obesity was associated with eF before T2D (p < 0.001), and perimenopausal age with apoA1 and haptoglobin increases (p < 0.0001)." (PMID 40428246, 2025). "It has been observed that a deficiency of haptoglobin is related to obesity-associated insulin resistance and hepatosteatosis." (PMID 40565086, 2025). "More recently, in Mexican adults and children, haptoglobin levels were found to be positively associated with obesity." (PMID 32752277, 2020). "High levels of interleukin-6 and haptoglobin are considered to be early biomarkers of inflammation associated with severe obesity with subsequent cardiovascular and type 2 diabetes risk." (PMID 27275205, 2015). "Haptoglobin levels had been reported to be associated with obesity, and evaluated for its role in inflammation in subjects with increased BMI." (PMID 27275205, 2015). "Of note, the increase in serum haptoglobin concentrations with obesity was unrelated to the haptoglobin polymorphism, because its genotypes were equally distributed among non-obese and obese women." (PMID 19440331, 2009). "Serum haptoglobin concentrations in premenopausal women are largely dependent on the haptoglobin polymorphism and on the presence of obesity, with insulin resistance and chronic inflammation possibly modulating this relationship." (PMID 19440331, 2009). "The increase in the synthesis of low MW isoforms of haptoglobin in obesity, and further when it associates IR, could be interpreted as a component of the low-degree inflammation state accompanying obesity, which is already present in early ages." (PMID 24949022, 2014). "Also, our present results indicate that serum haptoglobin levels of young premenopausal women are mostly dependent on the haptoglobin polymorphism and on obesity, with insulin resistance and chronic inflammation possibly contributing to this association." (PMID 19440331, 2009). "Obesity is found to be associated with low-grade inflammatory process characterized by the increase in circulating levels of pro-inflammatory cytokines such as transforming growth factor-β1, interleukin-6 and acute-phase protein (haptoglobin) in healthy obese adults." (PMID 27275205, 2015). "In conclusion, our results show that the HP2/HP2 genotype is associated with elevated TNF-α and IL-6, but not with hsCRP, levels in obese subjects, suggesting that the functional differences of HP subtypes could be associated with different outcomes of obesity." (PMID 24868113, 2014). "We hypothesized that the haptoglobin polymorphism might contribute to the increased oxidative stress and low-grade chronic inflammation frequently associated with polycystic ovary syndrome, obesity, and abnormalities of glucose tolerance." (PMID 19440331, 2009). "Haptoglobin was another up-regulated protein with nearly 4-fold increase in pregnant women with obesity and generalized gingivitis." (PMID 40366920, 2025). "No study thus far has assessed the respective impacts of elementary histological features (steatosis, NASH inflammatory activity, and fibrosis) adjusted according to T2DM and obesity on serum haptoglobin." (PMID 35327501, 2022). "In conclusion, T2DM is associated with abnormal levels of A2M, ApoA1, and haptoglobin independently of NAFLD, age, sex, obesity, and COVID-19." (PMID 35327501, 2022). "Haptoglobin is a circulating acute phase protein produced by the liver and adipose tissue, induced in prooxidant conditions, such as systemic inflammation or obesity." (PMID 36361589, 2022). "Here, in patients at risk of NAFLD, haptoglobin levels were positively associated with male sex, T2DM, and obesity, and surprisingly with the grade of steatosis in non–obese men, in univariate and multivariate analyses." (PMID 35327501, 2022). "In obesity, its expression is dramatically increased, and a potential role of haptoglobin as a macrophage chemoattractant in adipose tissue has been established." (PMID 30005082, 2018).